ZNF619 (zinc finger protein 619)
Description:
May be involved in transcriptional regulation.
Synonyms: FLJ90764
Tractability: PROTAC: ubiquitination databases record sites on it.
Gene: Protein-coding gene on chromosome 3 (40,477,113 to 40,491,053, forward strand). Ensembl gene ENSG00000177873.
Subcellular location: Nucleus
Subcellular location (Human Protein Atlas): Nucleoplasm; Intermediate filaments
Pathways (Reactome):
Gene expression (Transcription): Generic Transcription Pathway
Gene Ontology:
Molecular function: DNA-binding transcription factor activity, RNA polymerase II-specific; RNA polymerase II transcription regulatory region sequence-specific DNA binding; sequence-specific double-stranded DNA binding
Biological process: regulation of transcription by RNA polymerase II
Cellular component: nucleus
Genetic constraint (gnomAD): Loss-of-function variants: 9 observed, 13.15 expected, observed/expected ratio (o/e) 0.68, 90% interval 0.41 to 1.19. The upper end of that interval is the gene's LOEUF score, 1.19, which puts it in group 5 of 6, group 1 being the genes least tolerant of losing a copy. Missense variants: 635 observed, 701.5 expected, observed/expected ratio (o/e) 0.91, 90% interval 0.85 to 0.97. Synonymous variants: 236 observed, 258.27 expected, observed/expected ratio (o/e) 0.91, 90% interval 0.82 to 1.02.
Homologues: Orthologues: chimpanzee ZNF619 (98% identical), macaque ZNF619 (92% identical), dog ZNF619 (64% identical), pig ZNF619 (62% identical), Drosophila melanogaster CG3281 (23% identical), Drosophila melanogaster Phs (20% identical), Drosophila melanogaster CG2712 (20% identical). Paralogues in human: ZNF620 (44% identical), ZNF266 (35% identical), ZNF25 (35% identical), ZNF805 (35% identical), ZFP37 (35% identical), ZFP69B (35% identical), ZNF582 (34% identical), ZNF599 (34% identical), ZNF264 (34% identical), ZNF529 (34% identical), ZFP90 (34% identical), ZNF875 (33% identical), and 50 more.
Diseases named in the same sentence as ZNF619 in open-access papers:
ZNF619 is named in the same sentence as 3 diseases in open-access papers, as found by Europe PMC text mining. Sharing a sentence is not in itself a finding about the gene and the disease. The quoted sentences say what the papers report.
epilepsy (1 paper, 2025). A brain disorder characterized by episodes of abnormally increased neuronal discharge resulting in transient episodes of sensory or motor neurological dysfunction, or psychic dysfunction. "While LSR’s role in neuroinflammation, PARP1’s involvement in neuronal survival, and ZNF619’s regulation of transcription are consistent with epilepsy pathophysiology, these associations are based on a limited sample size and bulk‐tissue expression." (PMID 40624693, 2025). "Among all exposure genes, RP11-267M23.4, ENTPD3-AS, ZNF619, and RPL14 were demonstrated as risk factor to epilepsy, while NBL1, RNF157, and PARP1 were protective factors to epilepsy." (PMID 40624693, 2025). "We found that RP11-267M23.4, NBL1, ENTPD3-AS, RNF157, ZNF619, RPL14, and PARP1 showed causal relationship to epilepsy." (PMID 40624693, 2025). "Similarly, ZNF619, a zinc-finger protein, may be involved in regulating synaptic functions and neuronal plasticity, further suggesting its relevance in epilepsy." (PMID 40624693, 2025). "In the MR analysis with epilepsy as the outcome, we identified seven positive results: RP11-267M23.4, NBL1, ENTPD3-AS1, RNF157, ZNF619, RPL14, and PARP1." (PMID 40624693, 2025).
cancer (1 paper, 2025). A tumor composed of atypical neoplastic, often pleomorphic cells that invade other tissues. "ZNF619 belongs to the zinc finger protein family, commonly studied for its role in gene transcription regulation, often related to cancer and immune diseases." (PMID 40624693, 2025).
ZNF619 also shares sentences with these, for which no sentence is quoted: immune diseases (1 paper).